ISG15 (ISG15 ubiquitin like modifier)
Diseases named in the same sentence as ISG15 in open-access papers (continued):
Sharing a sentence is not in itself a finding about the gene and the disease.
ovarian carcinoma (continued). "Among DDX3X unique interactors, we identified ISG15 (interferon-stimulated gene 15), which in ovarian cancer is involved in tumor suppression by decreasing the expression levels of phospho-ERK1 and ERK downstream genes that are associated with cancer progression." (PMID 35954483, 2022). "In ovarian cancer patients, low ISG15 expression predicts poor prognosis." (PMID 35455671, 2022). "Moreover, ISG15 inhibits CSC-like phenotypes of cisplatin-resistant ovarian cancer cells and suppresses tumor formation in nude mice." (PMID 35455671, 2022). "Constructs containing −1767/+53 and −1237/+53 segments demonstrated similar suppressive effect on the luciferase activities, indicating that no regulatory element between −1767 and −1238 region responsible for suppressing ISG15 expression in cisplatin‐resistant ovarian cancer cells." (PMID 33797839, 2021). "Importantly, our data showed that ISG15 positive expression was correlated with good prognosis in the patients with ovarian cancer." (PMID 33797839, 2021). "In addition, ISG15 downregulation promoted CSC‐like features of cisplatin‐sensitive ovarian cancer cells." (PMID 33797839, 2021). "Since ISG15 has been shown to be secreted from monocytes and lymphocytes, we further evaluated whether ovarian cancer cells expressing high levels of endogenous ISG15 would secrete ISG15 protein into the extracellular space." (PMID 30469497, 2018). "In addition, increased secretion of ISG15 by ovarian cancer cells activated NK cells via paracrine signaling, which subsequently increased CD8+ cell proliferation rates." (PMID 30469497, 2018). "ISGylation of ERK may therefore inactivate ERK and mediate the suppressor effect of ISG15 on ovarian cancer progression." (PMID 30469497, 2018). "Indeed, deregulated ISG15 expression has been found in response to diverse cancer chemotherapeutic agents, such as paclitaxel in the treatment of ovarian carcinomas and 5-fluorouracil in the therapy of oesophageal cancer." (PMID 18627608, 2008). "Moreover, ISG15 is found to be downregulated in CDDP-R ovarian cancer." (PMID 37174688, 2023). "Therefore, is possible that DDX3X exerts an oncosuppressive role in ovarian cancer by acting on the negative regulation of NFκB2 at different levels by direct interaction with NF-κB or by enhancing the expression of ISG15 that in turn suppresses NFκB2 activity." (PMID 35954483, 2022). "Hence, it was inferred that there were regulatory elements spanning −1236/−897 and −896/−412 region, which might be responsible for suppressing ISG15 expression in cisplatin‐resistant ovarian cancer cells." (PMID 33797839, 2021). "However, other ISG15 targets besides ERK1 may also be involved in suppressing ovarian cancer progression." (PMID 30469497, 2018). "However, clinical correlation studies showed that high levels of ISG15 expression in ovarian cancer cells indeed correlated with improved survival, and our in vitro and in vivo data showed that endogenous ISG15 suppressed ovarian cancer growth and increased apoptosis." (PMID 30469497, 2018). "In ovarian cancer cell lines SKOV3 and A2780, CS knockdown increased the mRNA levels of ISG15, IRF7, CASP7, and DDX58, according to microarray and qPCR studies." (PMID 41515967, 2025). "We also found increased ISG15 expression and an increased ISGylation profile in HGSOC patient tissues and in tumour and ascites derived from an orthotopic ovarian cancer mouse model along with USP18 and ISGylating enzyme TRIM25." (PMID 38939897, 2024). "In this study, we identified significantly elevated ISG15 protein expression in HGSOC patient ascites, ascites derived primary ovarian cancer cells (POCCs), POCC small extracellular vesicles (sEVs) as well as metastatic tissue." (PMID 38939897, 2024). "In this regard, ISG15 has been reported to inhibit ABCC2 expression and re-sensitize CDDP-R ovarian cancer cells." (PMID 37174688, 2023).
ovarian carcinoma (continued). "Coexpression of ISG15 and KLF family members was analysed in ovarian cancer using online data (starBase v3.0 project)." (PMID 33797839, 2021). "ISG15 expression was explored in two pairs of cisplatin‐sensitive (SKOV3 and A2780) and cisplatin‐resistant (SKOV3/DDP and A2780/DDP) ovarian cancer cell lines." (PMID 33797839, 2021). "Recently, our group have also revealed ISG15 suppresses translation of ABCC2 via ISGylation of hnRNPA2B1 and enhances drug sensitivity in cisplatin‐resistant ovarian cancer cells." (PMID 33797839, 2021). "Increased NF-κB signaling and elevated ISG15 expression were recently observed also in BRCA1 mutants of fallopian tube epithelial cells and in ovarian cancer cells." (PMID 31903170, 2019). "In this experiment, four ovarian cancer cell lines (ALST, OV90, OVCA420, and OVCA432) expressing various levels of endogenous ISG15 were cultured in serum free media for 48 hours." (PMID 30469497, 2018). "Our findings suggest that ISG15 may drive the progression and metastasis of HGSOC and serve as a potential biomarker for ovarian cancer prognosis." (PMID 38939897, 2024). "ISG15, SNCA, RIPK2, PLCG2, RHOU, TRIB2 and ELP2 influenced the OS and PFI of ovarian cancer patients in the TCGA-OV dataset, while RIPK2 also affected the OS and PFI of ovarian cancer patients treated with Taxol in the GSE30161, GSE32062 and GSE63885 datasets." (PMID 35477477, 2022). "Furthermore, ISG15 can inhibit the protein translation of ABCC2 and increase drug sensitivity in cisplatin-resistant ovarian cancer cells." (PMID 35455671, 2022). "ISG15 induced CD8 T cells and inhibited the progression of ovarian cancer." (PMID 34109184, 2021). "The current study identified that both ectopic wild type and nonISGylatable mutant ISG15 expression inhibited CSC‐like phenotypes of cisplatin‐resistant ovarian cancer cells." (PMID 33797839, 2021). "Our work showed that only conjugatable ISG15 (wild type) increased the sensitivity of cisplatin in ovarian cancer cells, while both conjugatable and nonISGylatable mutant ISG15 were involved in CSC‐like characters." (PMID 33797839, 2021). "Previous studies have demonstrated that extracellular ISG15 not only acts as an immune adjuvant to enhance the anti-tumour immunity of CD8+ T cells, but also activates NK cells and increases their production of IL-2 and IFN-γ cytokines, resulting in the proliferation of ovarian cancer CD8+ T cells." (PMID 37217923, 2023). "Additionally, ISG15 can also trigger the activation of CD8+ T cells through the mediation of NK cells, which then elevates its increase in numbers, thereby inhibiting the progression of ovarian cancer." (PMID 35538543, 2022). "Our data indicated that downregulating ISG15 expression, via weakening effect of KLF12, might be considered as new therapeutic strategy to inhibit CSC phenotypes in the treatment of cisplatin‐resistant ovarian cancer." (PMID 33797839, 2021). "Since ISG15 expression in ALST and OVCA5 cancer cells can be induced in the presence of interferon, we further evaluated whether interferon treatment regulates ERK signaling via induction of ISG15 in ALST and OVCA5 ovarian cancer cells." (PMID 30469497, 2018). "Obvious negative correlation of ISG15 was observed with KLF12 (R = −0.287, P = 1.25e−8) in 379 ovarian cancers." (PMID 33797839, 2021). "In addition, knock‐down of ISG15 did not alter the responsiveness to cisplatin, but promoted CSC‐like features of sensitive ovarian cancer cells." (PMID 33797839, 2021).
nasopharyngeal carcinoma (20 papers, 2015 to 2025). A carcinoma arising from the nasopharyngeal epithelium. "SPP1 plays an essential role in maintaining macrophage M2 polarization, and ISG15 is associated with poor prognosis in patients with nasopharyngeal carcinoma and induces a macrophage M2-like phenotype." (PMID 36551288, 2022). "ISG15 expression is linked to poor prognosis of patients with nasopharyngeal carcinoma (NPC)." (PMID 36319753, 2022). "In nasopharyngeal cancer, high ISG15 correlated with frequent local cancer recurrence and shorter overall survival." (PMID 28186990, 2017). "ISG15 processing promotes macrophage polarization towards an M2-like phenotype, enhancing the migration and tumorigenicity of nasopharyngeal carcinoma (NPC) cells." (PMID 40103488, 2025). "Nasopharyngeal carcinoma (NPC) cells secrete IFN-stimulated gene 15 (ISG15), which remodels macrophages into the M2 subtype by activating the LFA-1/SFK/CCL18 axis." (PMID 40607254, 2025). "ISG15 is expressed on nasopharyngeal carcinoma (NPC) cells and is related to a poor prognosis of patients with NPC." (PMID 35159348, 2022). "We had reported that ISG15 expressed on nasopharyngeal carcinoma (NPC) cell and relates to poor prognosis of patients with NPC." (PMID 33424843, 2020). "We previously reported that ISG15 expressed on nasopharyngeal carcinoma (NPC) cells and related to poor prognosis of patients with NPC." (PMID 33424843, 2020). "In nasopharyngeal carcinoma tissues, the number of ISG15+ CD163+ macrophages were significantly higher than that of non-cancerous nasopharyngeal epithelium, suggesting the infiltration of ISG15+ CD163+ macrophages relate to the development of NPC." (PMID 33424843, 2020). "Here, using RNA-seq profiling analysis, we identified ISG15 as a differentially expressed gene in nasopharyngeal carcinoma (NPC) and validated its overexpression in NPC samples and cells." (PMID 26919245, 2016). "ISG15 upregulation has been reported to promote cancer stem cell phenotype and increases cell resistance to cisplatin (DDP) treatment in nasopharyngeal carcinoma, while ISG15 downregulation increases cisplatin resistance in lung cancer." (PMID 33797839, 2021). "Further analysis has found that ISG15 could be secreted by nasopharyngeal carcinoma cells and induced macrophages to M2 polarization, thereby inhibiting the antitumor activity of T cells and accelerating tumor progression, indicating that ISG15 is an important molecule in tumor microenvironment." (PMID 34696780, 2021). "Additionally, the increased migration of nasopharyngeal carcinoma cells, induced by CCL18 from the supernatants of ISG15-treated macrophages, was significantly reduced following treatment with this LFA-1 inhibitor." (PMID 39911389, 2025). "Similarly, IFN-β has also been linked to cancer stemness promotion in PDAC by inducing TAM ISG15 ubiquitin like modifier (ISG15) secretion, which has also been related to CSC phenotype induction in nasopharyngeal carcinoma." (PMID 34571733, 2021). "Similarly, ISG15 expression promoted a cancer stem cell phenotype in nasopharyngeal cancer cells; however, it is not known if this was the result of ISG15 acting as a free or secreted protein or through ISGylation." (PMID 39159817, 2024).
systemic lupus erythematosus (20 papers, 2016 to 2026). An autoimmune multi-organ disease typically associated with vasculopathy and autoantibody production. "For instance, current findings indicate that ISG15 mRNA levels in the blood of systemic lupus erythematosus patients are significantly higher than those in healthy controls, and ISG15 expression is closely linked to disease activity." (PMID 41193953, 2025). "Autosomal recessive ISG15 deficiency causes type I interferonopathy with systemic lupus erythematosus (SLE) and inflammatory myositis." (PMID 35159348, 2022). "ISG15 expression and Treg dynamics were analysed in vitro and ex vivo from patients with chronic hepatitis C, with lupus and ISG15 deficiency." (PMID 33376595, 2020). "Ex vivo, in systemic lupus erythematosus patients, higher levels of ISG15 are associated to reduced STAT1 phosphorylation in response to IFNα, and also to increased frequencies of Tregs, characterising active disease." (PMID 33376595, 2020). "A recent study reported a population of ISG15 Tregs in human patients where the authors suggest ISG15 is involved in the maintenance of Treg populations during inflammatory conditions such as systemic lupus erythematosus." (PMID 38085267, 2024). "Some single gene variants (SAMHD1, RNASEH2ABC, ADAR1, IFIH1, ISG15, ACP5, TMEM173) can cause monogenic lupus." (PMID 35783307, 2022). "Meanwhile, the expression levels of IFN-I signature genes (ISGs), such as Mx1, Irf7, Oas1, and Isg15, were increased in the renal tissues of KI lupus mice compared with WT lupus mice." (PMID 35788118, 2022). "Higher IFNγ production was found in total PBMCs that were stimulated with NETs from lupus patients that previously had shown to contain ISG15 compared to cells stimulated with NETs from healthy controls (%IFNγ 6.5[6.31–10.1] vs 3.5[1.7–5.1]) p < 0.05)." (PMID 33176801, 2020). "Accordingly, we found increased expression of ISG15 in lupus NETs (both spontaneous and LPS-induced) compared to healthy controls (p < 0.05)." (PMID 33176801, 2020). "This leads to the identification of ISG15-secreting plasmablasts/PCs in patients with active systemic lupus erythematosus." (PMID 27357150, 2016). "In SLE patients, neutrophil extracellular traps are characterized by the expression of ISG15, which further confirms that ISG15 may act as a persistent proinflammatory stimulus in the pathogenesis of lupus." (PMID 39445158, 2024). "Another prototypic example for the pathogenic role of B cells is systemic lupus erythematosus (SLE), where ISG15-secreting plasmablast expansions are a hallmark of activity and dysregulated GC reactions mediate the positive selection of high-affinity autoantibodies driving pathogenesis." (PMID 35488094, 2022). "In lupus patients, high ISG15 expression sustains high Treg frequencies in active disease." (PMID 33376595, 2020). "Although higher autoantibody levels were identified in patients with ISG-15 deficiency compared to the age-matched controls, there are no reports of lupus patient carrying ISG15 or USP18 mutations." (PMID 32151092, 2020). "NETs containing ISG15 from SLE patients induce IFNγ production from diverse cellular subsets: To address the functional impact of ISG15 on the NETs from lupus patients, the production of IFNγ in subsets of T lymphocytes (CD4+ and CD8+) and NK cells was evaluated by multiparametric flow cytometry." (PMID 33176801, 2020). "Consequently, is more plausible that ISG15 coming from lupus NETs is in a free, extracellularly, cytokine-like form accounting, at least in part, for durable pro-inflammatory responses." (PMID 33176801, 2020). "This ISG15-FAO regulatory interaction was also evident in systemic lupus erythematosus (SLE)-associated interferonopathy and in primary monocytes from SLE individuals that exhibited increased ISG15 levels and reduced FAO rates." (PMID 41743980, 2026).
systemic lupus erythematosus (continued). "In this study, we employed Mendelian randomization to investigate the potential causal relationship between five genes, namely, DDX58, IFIH1, IRF7, STAT1, and ISG15, and systemic lupus erythematosus (SLE)." (PMID 39445158, 2024). "Therefore, we postulate that Isg15 may play an important role in renal pathology in lupus and may serve as a potential marker of kidney inflammation and degree of injury in SLE." (PMID 32552896, 2020). "This is consistent with other studies that have shown the implication of ISG15 and MX1 in the progression of lupus and some of its crucial pathological events, such as lymphocytopenia and lupus nephritis." (PMID 40574053, 2025). "Therefore, ISG15 may act as a persistent proinflammatory stimulus in the pathogenesis of lupus." (PMID 39445158, 2024). "Therefore, ISG15 in lupus pathogenesis may act as a durable proinflammatory stimulation." (PMID 35757684, 2022). "The differential expression levels of the Coro1A, Isg15 and Arhgdib in kidney mouse tissues, as determined by targeted MRM-MS analysis, were found to be significantly upregulated in the kidneys of Sle123 lupus-prone compared to control mice." (PMID 32552896, 2020). "Nevertheless, it is the first study to address the in vitro, in silico and ex vivo role of ubiquitin and NETosis-released-ISG15, their impact on cellular responses from SLE patients as well as the improvement in our knowledge of the pathophysiology of lupus and autoimmunity." (PMID 33176801, 2020).
lung carcinoma (19 papers, 2016 to 2025). "Accordingly, elevated expression of SIRT1 and ISG15 was associated with poor prognosis in lung cancer patients, a finding that could be translated for lung cancer patient stratification and disease outcome evaluation." (PMID 38443596, 2024). "Accordingly, SIRT1 ISGylation promoted lung cancer progression and limited lung cancer cell sensitivity to DNA damage-based therapeutics in in vivo and in vitro models, and elevated expression of SIRT1 and ISG15 was associated with poor prognosis in lung cancer patients." (PMID 38443596, 2024). "Additionally, high levels of SIRT1 and ISG15 in lung cancer tissues were linked to worse outcomes." (PMID 38443596, 2024). "To substantiate these conclusions, we selected 12 lung cancer patients undergoing anti-PD-1 therapy from the Nanjing Drum Tower Hospital for a follow-up study, and confirmed that patients with high ISG15 expression were more responsive to anti-PD-1 therapy." (PMID 40208307, 2025). "Significant induction of both ISG15 expression and protein ISGylation conjugates formation in the presence of doxorubicin was observed in A549 and H23 cells derived from lung cancer and in HeLa cells derived from cervical cancer." (PMID 38443596, 2024). "To further extend our observations to a clinicopathologically relevant context, we analyzed the protein expression levels of SIRT1 and ISG15 in NSCLC patients-derived lung cancer tissues." (PMID 38443596, 2024). "Doxorubicin induced ISGylation of endogenous SIRT1 in both A549 and H23 cells derived from lung cancer, in which it was robustly able to induce ISG15 expression and protein ISGylation conjugates formation." (PMID 38443596, 2024). "The research, conducted on human cells, mice, and human lung cancer tissues, revealed that when ISG15 conjugates to SIRT1, it boosts SIRT1’s activity, encouraging tumor growth and reducing the effectiveness of a chemotherapy drug." (PMID 38443596, 2024). "The levels of ISG15 mRNA and protein were significantly higher in lung cancer tissues than in adjacent normal tissues." (PMID 38443596, 2024). "In line with our analyses of the CCLE and TCGA databases, the protein levels of ISG15 and ISGylation conjugates were high in eight of the lung cancer tissues (72.7%)." (PMID 38443596, 2024). "The highest-ranked genes in both cohorts of primary lung cancers and LC-BrMs included CCNL2, DVL1, ATAD3A, AGRN, and ISG15, where mutation patterns were clustered for the patients." (PMID 39593114, 2024). "From the perspective of clinical relevance, we revealed that SIRT1 and ISG15 were upregulated in primary lung adenocarcinoma tissues from lung cancer patients compared to the corresponding adjacent normal tissues." (PMID 38443596, 2024). "The E1 enzyme UBA7 (also named UBE1L) of the ISG15 covalent modification system is located on chromosome 3p21, and 3p21 is missing in lung cancer patients; thus, UBA7 is often lowly expressed in lung cancer." (PMID 36771004, 2023). "As well, interferon-stimulated gene 15 (ISG15) is induced by type I interferon and is correlated with hypertension and lung cancer." (PMID 36685671, 2023). "The findings presented here establish a critical role for ISG15 complex formation with 14-3-3ζ protein that alters 14-3-3ζ protein stability, lung cancer metastases in murine and human lung cancer survival." (PMID 35387560, 2022). "Given the similar response of HeLa and A549 cells to IFN-γ, to ISG15 induction, and to protein ISGylation, we took advantage of existing wild-type and knockout (KO) lines of the human lung carcinoma epithelial line A549." (PMID 33024031, 2020). "IP assays of human lung cancer cells transfected with HA-tagged ISG15 revealed that both exogenous and endogenous PTEN proteins are mono-ISGylated resulting in the expected molecular weight ~75 kDa species." (PMID 27980214, 2017).